MMP1 (matrix metallopeptidase 1)
Diseases named in the same sentence as MMP1 in open-access papers (continued):
Sharing a sentence is not in itself a finding about the gene and the disease.
renal carcinoma (2 papers, 2022 to 2025). A carcinoma arising from the epithelium of the renal parenchyma or the renal pelvis. "Based on these findings, our study confirms that EA inhibits MMP1 expression by downregulating RUNX2, thereby suppressing the migration and invasion abilities of renal cancer cells." (PMID 40386045, 2025). "Overall, our study demonstrated that the inhibitory effect of EA on renal cancer cell migration and invasion is mediated through the inhibition of the RUNX2/MMP1 axis." (PMID 40386045, 2025). "Our study shows that SIGIRR downregulation in RCC cells unleashes an inflammatory signaling intrinsic to renal cancer cells that leads to NFKBIZ activation, IL6 induction, MMP1 upregulation, and notably higher levels of PD-L1 and ICAM1 expression." (PMID 35814450, 2022). "The induction of MMP1 and ICAM was previously reported to be activated by IL1 in renal cancer cells, suggesting that this pathway could favor tumor metastasis." (PMID 35814450, 2022).
retinal degeneration (2 papers, 2017 to 2019). Degeneration of the retina. "Associations between MMPs and the IL-1 family have also been found in other retinal degenerations, with increased levels of MMP-1, MMP-9, MMP-12, and IL-1β found in the vitreous of patients with POAG, as well as elevated MMP-9 and IL-1Ra observed in the vitreous and tears of ROP infants." (PMID 31379825, 2019). "Matrix metalloproteinases (MMPs), responsible for the protein degradation of the extracellular matrix (ECM), have also been linked to IL-1β in retinal degenerations, with wet AMD patients carrying SNPs in MMP-1 and MMP-7 genes found to have a higher serum concentration of IL-1β." (PMID 31379825, 2019). "The expression of macrophage markers (CD14 and MAC-1), neutrophils (Ly6G), monocyte chemoattractant protein (MCP-1), angiogenesis marker (VEGF) and matrix metalloproteases (MMP-1 and MMP-2) were also upregulated in retinal degeneration models CBA/J and NOD.SCID-rd1." (PMID 28258056, 2017).
rhabdomyosarcoma (2 papers, 2013 to 2014). A rare aggressive malignant mesenchymal neoplasm arising from skeletal muscle. "A study of the immunohistochemical expression of MMPs and TIMPS in human rhabsomyosarcoma revealed strong MMP-1, -3 and -9 expression in rhabdomyosarcoma, alveolar RMS greater than embryonal RMS." (PMID 24190483, 2014). "A study of the immunohistochemical expression of MMPs and TIMPS in human rhabdomyosarcoma demonstrated strong MMP-1, -3 and -9 expression in rhabdomyosarcoma, alveolar RMS greater than embryonal RMS." (PMID 23900236, 2013).
rheumatic heart disease (2 papers, 2014 to 2018). An autoinflammatory condition following an infection with Group A Beta Hemolytic Streptococcus (GABHS), in which the heart is attacked by antibodies formed in reaction to a recent GABHS infection. "ROC curve analysis demonstrates plasma PICP, total MMP-1 and PIIINP as significant predictors of rheumatic heart disease.PICP performed better than MMP-1, PIIINP or TIMP-1 with AUC of 0.95." (PMID 24603967, 2014).
rosacea (2 papers, 2016 to 2024). A chronic erythematous skin disorder that affects the face. "Chronic ultraviolet A (UVA) irradiation can induce the overexpression of MMP-1, which is associated with the dermal collagen degeneration seen in rosacea." (PMID 27649161, 2016). "Together, these findings suggest that remodeling of the vasculature and dermal matrix by VEGF, FGF2, and MMP-1 and the production of ROS and ER stressors after UV radiation provide a logical framework explaining UV radiation as a triggering factor for rosacea." (PMID 27649161, 2016). "In addition, connective tissue hyperplasia in some rosacea patients is related to the persistence of inflammation, the activation of mast cells and the release of MMP1, MMP9, IL-6, and histamine, and the increased activity of the TRPs14." (PMID 38321132, 2024). "MMPs are believed to be associated with the neurodegenerative diseases and an increased expression of MMP-1 and MMP-9 has also been observed in rosacea." (PMID 27649161, 2016).
schizophrenia (2 papers, 2012 to 2017). A major psychotic disorder characterized by abnormalities in the perception or expression of reality. "Our finding of increased TIMP1 and decreased MMP1 is consistent with previous reports and suggests a cytoprotective role of this pathway in the brains of schizophrenia patients." (PMID 23118852, 2012).
scoliosis (2 papers, 2019 to 2022). A congenital or acquired spinal deformity characterized by lateral curvature of the spine. "MMP-1 and MMP-3 immuno-positive cells and cell clusters were abundant in fissured and disrupted regions in herniated and degenerated discs in comparison to (scoliosis) controls, and thus were comparable to unconstrained explant tissues." (PMID 31871771, 2019).
spondylitis (2 papers, 2023 to 2025). The inflammation of a vertebra. "In the present study, we investigated the effects of doxycycline as an MMP-1 inhibitor in patients with spondylitis TB." (PMID 36743515, 2023).
stress incontinence (2 papers, 2015 to 2018). "We identified 2 unpublished studies from the United States, and 2 published studies of Polish61,62 and Italian44 samples assessing associations between MMP1 variants and stress incontinence or prolapse." (PMID 25111588, 2015).
synovial sarcoma (2 papers, 2014 to 2025). "Pretreatment with myricetin and its effects on decreased the up-regulation of matrix metalloproteinase 1 (MMP-1) and IL-6, as well as inhibiting the phosphorylation of p38 and JNK in human synovial sarcoma cells in vitro." (PMID 40362425, 2025).
type 1 diabetes (2 papers, 2017). "Despite these limitations, our results showed largely consistent results throughout the three different studies with regard to the associations between MMP-1, MMP-2 and PP in individuals with type 1 diabetes." (PMID 29070037, 2017). "In patients with type 1 diabetes followed for a median of 12 years, higher plasma MMP-2 levels are associated with incident CVD and higher plasma MMP-1, MMP-2, MMP-3 are associated with all-cause mortality." (PMID 28446168, 2017). "In individuals with type 1 diabetes, MMP-1 (inversely) and MMP-2 and -3 (both positively) were associated with markers of arterial stiffening (PP and cfPWV)." (PMID 29070037, 2017). "Therefore, the aim of our study was to investigate associations between circulating levels of MMP-1, -2, -3, -9, and -10 and of TIMP-1 with markers of arterial stiffness, i.e. cfPWV and PP, in individuals with type 1 diabetes." (PMID 29070037, 2017). "In view of these considerations, we investigated associations, in type 1 diabetes, between plasma MMP-1, -2, -3, -9 and -10, and TIMP-1 and incident non-fatal and fatal cardiovascular events, as well as all-cause mortality, in a prospective study with more than 12 years of follow-up." (PMID 28446168, 2017).
Varicose veins (2 papers, 2014 to 2016). Enlarged and tortuous veins. "The subtraction showed a decrease in active MMP-1 in varicose veins (SDv and LDv; n = 6) as compared with healthy SV (n = 4)." (PMID 24505358, 2014). "On the contrary, it has been demonstrated that in varicose veins decreased MMP-1 and MMP-2 activities could result in accumulation of collagens and thickening of the vascular wall." (PMID 27362269, 2016). "Increased collagen content has been shown in varicose vein pathology, for this reason active collagenase MMP-1 was measured in the present study and we have calculated the active MMP-1/TIMP-1 and MMP-1/TIMP-2 ratios." (PMID 27362269, 2016). "Active MMP-1 and total MMP-2 concentrations were significantly decreased in varicose veins while the tissue inhibitors of metalloproteinases (TIMP -1 and -2), were significantly increased, probably explaining the increased collagen content found in LDv." (PMID 24505358, 2014). "Our results describe a decrease in active MMP-1, total MMP-2 (while total MMP-1 is not modified in varicose veins) and an increase in TIMP-1 and TIMP-2 concentrations in varicose veins." (PMID 24505358, 2014).
viral infection (2 papers, 2017 to 2025). "MNK is thought to increase translation, and therefore the phenotype of increased MMP-1 after MNK inhibition may be due to reduced inhibitory transcription factor production, as has been demonstrated for type I interferons in viral infection." (PMID 28570642, 2017).
acute lymphoblastic leukemia (1 paper, 2025). Leukemia with an acute onset, characterized by the presence of lymphoblasts in the bone marrow and the peripheral blood. "A possible protective effect of the MMP-1 rs1799750 1G allele has been suggested in childhood acute lymphoblastic leukemia." (PMID 40724896, 2025).
adenovirus infection (1 paper, 2023). "The expression levels of MMP1, IL6, IL8, and PTGS2 increased upon CH25H overexpression via adenovirus infection in human GFs." (PMID 38036731, 2023).
adhesive capsulitis (1 paper, 2024). "It was demonstrated that the mRNA expression of MMP-2 in samples from patients with adhesive capsulitis was found more often than MMP-1 or MMP-3." (PMID 38381214, 2024). "When the peripheral blood values of matrix metalloproteases and tissue inhibitors of metalloproteases (TIMP) in patients with adhesive capsulitis were examined, MMP-1 level was significantly lower when compared with the control group whereas the TIMP levels were increased." (PMID 38381214, 2024). "Considering that MMP-1 is a factor commonly associated with adhesive capsulitis, it is possible that the relationship of MMP-1 to lamin A/C could contribute to the explanation as to why weaker expression of lamin A/C in patients with adhesive capsulitis were documented." (PMID 38381214, 2024).
alcoholic-steatohepatitis (1 paper, 2025). "The multitargeted effects of T4OL—simultaneously reducing inflammation (NF-κB1/IL-6), hypoxia (HIF-1α), and fibrosis (TGF-β1/MMP1)—make it a promising candidate for ALD treatment, particularly in alcoholic-steatohepatitis and early fibrosis stages." (PMID 40572736, 2025).
amyloidosis (1 paper, 2025). A disorder characterized by the localized or diffuse accumulation of amyloid protein in various anatomic sites. "In the SMC-calc vs. SMC comparison based on limma, clusters related to high-density lipoprotein (HDL) assembly (PF4V1, APOA1, LPXN, AFP, A2M, and MMP1) and amyloidosis (CX3CL1, APOE, PLIN3, TGFBI, and CH25H) were identified." (PMID 41301179, 2025).
amyotrophic lateral sclerosis (1 paper, 2021). Amyotrophic lateral sclerosis (ALS) is a neurodegenerative disease characterized by progressive muscular paralysis reflecting degeneration of motor neurons in the primary motor cortex, corticospinal tracts, brainstem and spinal cord.
anemia (1 paper, 2020). A reduction in the number of red blood cells, the amount of hemoglobin, and/or the volume of packed red blood cells. "Since CKD and anemia were independently associated with the combination of high PICP and low CITP:MMP-1 ratio and showed a higher prevalence in HFpEF patients, we investigated whether the association of the biomarker combination with HFpEF could be influenced by these factors." (PMID 32028612, 2020).
Anxiety (1 paper, 2016). Intense feelings of nervousness, tension, or panic often arise in response to interpersonal stresses. "At the behavioral level, astrocyte-derived MMP-1 induces several phenotypes associated with altered synaptic plasticity including decreased anxiety and deficits in sociability and hippocampal dependent memory." (PMID 27762280, 2016).
aortic regurgitation (1 paper, 2020). "However, MMP1 rs1799750 and MMP9 rs3918242 seem to be associated with the degree of aortic regurgitation in these patients." (PMID 33029260, 2020). "However, rs1799750 MMP1 and rs3918242 MMP9 seem to be associated with the degree of aortic regurgitation." (PMID 33029260, 2020). "However, we have shown that the MMP1 and MMP9 genes may partially contribute to the incidence of aortic regurgitation." (PMID 33029260, 2020).
aortic valve calcification (1 paper, 2019). "We have, for instance, reported an association between the MMP1 rs1799750 single nucleotide polymorphism and aortic valve calcification in surgical specimens using this method." (PMID 31877754, 2019).
Arterial thrombosis (1 paper, 2025). The formation of a blood clot inside an artery. "It is also important to mention that MMP-1 rs1799750 created a tendency towards an increased risk of arterial thrombosis in MPN patients." (PMID 40724896, 2025). "In our study, the MMP-1 rs1799750 1G2G genotype (compared to 2G2G) showed a trend toward increased arterial thrombosis risk (OR = 3.200, 95% CI 0.956–10.714, p = 0.059), indicating a possible association that warrants further investigation in larger cohorts." (PMID 40724896, 2025). "Moreover, MPN patients carrying the MMP-1 rs19799750 1G2G genotype (vs 2G2G) tended to have an increased risk of arterial thrombosis (p = 0.059), while the MMP-3 rs3025058 6A6A genotype (compared to 5A5A) showed a tendency towards decreased arterial thrombosis (p = 0.058)." (PMID 40724896, 2025).
Ascites (1 paper, 2017). Accumulation of fluid in the peritoneal cavity (between the layers of the peritoneum that lines the abdomen). "Collectively, our findings revealed that the EVs containing MMP1 mRNA are present in patient-derived ascites and might reflect the status of the patients." (PMID 28262727, 2017).
aspergillosis (1 paper, 2022). Aspergillosis is an infection, growth, or allergic response caused by the Aspergillus fungus. "Therefore, we further investigated MMP1, IL-8, and caspase-3 in possible IPA and CAPA patient sera to evaluate their potential as discriminative markers for different clinical manifestations of aspergillosis." (PMID 35205926, 2022).
astroglioma (1 paper, 2016). "We discovered that C2 ceramide strongly inhibits the expression and enzymatic activities of MMP-1, -3, and -9 induced by phorbol myristate acetate (PMA) in human astroglioma cells." (PMID 27043542, 2016). "In the present study, we demonstrate that C2 ceramide inhibits MMP-1, -3, and -9 expressions in PMA-stimulated human astroglioma cells." (PMID 27043542, 2016).
Atrophy (1 paper, 2014). Any weakening or degeneration, especially through lack of use. "Epidermal and dermal atrophy, reduced numbers of fibroblasts, loss of type I procollagen expression, and increased MMP-1, 3, and 9 expression are observed in intrinsically aged human skin." (PMID 24667799, 2014).
autism (1 paper, 2016). Persistent deficits in social interaction and communication and interaction as well as a markedly restricted repertoire of activity and interest as well as repetitive patterns of behavior. "Given that astrocyte activation is observed with autism and FXS16, 60, it is tempting to speculate that astrocyte derived proteases contribute to altered neuroplasticity in these conditions and more specifically, that the MMP-1/PAR1 signaling axis could represent a therapeutic target." (PMID 27762280, 2016).
AV block (1 paper, 2020). "The MMP1 serum protein level was significantly higher in the AV block group than in the control group (6568.9 ± 5748.6 pg/ml vs. 4730.5 ± 3377.1 pg/ml, P = 0.019)." (PMID 32555355, 2020).
basal cell tumours (1 paper, 2008). "When the collagen was exposed to organ culture fluid from human basal cell tumours of the skin (containing a high level of active matrix metalloproteinase-1 (MMP-1)), degradation of the collagen matrix occurred." (PMID 18443597, 2008). "The fragmentation pattern produced from intact type I collagen by exposure to organ culture from either UV-treated skin or basal cell tumour tissue was characteristic of MMP-1 (i.e., with $3over 4$- and $1over 4$-sized fragments being the major degradation products)." (PMID 18443597, 2008).
Behcet disease (1 paper, 2020). A chronic, relapsing, multisystemic vasculitis characterized by mucocutaneous lesions, as well as articular, vascular, ocular and central nervous system manifestations. "However, there is a low synovial MMP-1 level in the OA cases in Turkey compared with the controls of other non-RA diseases, including Behcet's disease and familial Mediterranean fever." (PMID 33331536, 2020).
bone cancer (1 paper, 2020). A primary or metastatic malignant neoplasm affecting the bone or articular cartilage. "Involved in bone cancer metastasis acting alongside MMP-1 and MMP-11." (PMID 32116759, 2020).
brain glioma (1 paper, 2022). A malignant glioma that involves the brain. "In the case of brain gliomas, an increase in MMP-1 expression is mainly observed in grade IV gliomas." (PMID 36291686, 2022).
burn (1 paper, 2024). A traumatic injury involving interruption of tissue cohesiveness that results from exposure to caustic chemicals, extreme heat, extreme cold or excessive radiation. "In short, the effect of skin burn on patients is to regulate the expression of immune-related genes UPP1, MMP1, MMP3, and skin regeneration-related gene DPT, which may be the key target for the treatment of skin burn." (PMID 36103997, 2024).
carcinoid (1 paper, 2014). "let-7 overexpression inhibited growth of carcinoid cell lines, and let-7 inhibition increased protein content of the transcription factor BACH1 and its targets MMP1 and HMGA2, all known to promote bone metastases." (PMID 25546138, 2014).
carcinoma in situ (1 paper, 2022). "Moreover, consistent with IHC findings, qRT-PCR results revealed that the mRNA levels of MMP1 in carcinoma in situ/SCC samples were highly upregulated compared with normal tongue samples." (PMID 36105241, 2022).
cardiac interstitial fibrosis (1 paper, 2022). "More importantly, renalase treatment significantly alleviates cardiac interstitial fibrosis, followed by the increased cardiac expression of MMP-1, lower expression of TIMP-1, and TGF-β, and decreased phosphorylated ERK 1/2 levels." (PMID 35711341, 2022).
cardiomyopathy (1 paper, 2023). A disease of the heart muscle or myocardium proper. "For example, abnormally high expression levels of cardiac-specific MMP1 lead to the loss of collagen and a decline in cardiac contractility, leading to cardiomyopathy." (PMID 37831322, 2023).
cataract (1 paper, 2016). Partial or complete opacity of the crystalline lens of one or both eyes that decreases visual acuity and eventually results in blindness. "The concentrations of MMP-1 and MMP-9 in the aqueous humors of 15 cataract patients and 25 DME patients were compared." (PMID 27467659, 2016).
cervical tumor (1 paper, 2017). "Staurosporine (a kinase inhibitor) appears to induce an anti-tumor response in the cervical tumor microenvironment, and inhibits cancer progression and metastases through suppression of MMP-1 and MMP-2." (PMID 29267213, 2017).
Cholestatic liver disease (1 paper, 2021). "Whether concurrent inhibition of MMP-1 and MMP-13 can act synergistically with ADAM17 remains uncharacterized in cholestatic liver disease." (PMID 35095853, 2021).
Chronic colitis (1 paper, 2014). A chronic inflammatory disease of the large intestine (colon, cecum and rectum). "Analysis of mice with induced chronic colitis revealed an increase of ceramide combined with induction of matrix metalloproteinase 1 (MMP-1) by cytokines like TNF-α and IL-1β." (PMID 25228885, 2014).
chronic skin ulcers (1 paper, 2017). "In chronic skin ulcers, prolonged MMP1 activity can have a critical effect on the re-epithelialization of tissues." (PMID 28494022, 2017).
chronic venous insufficiency (1 paper, 2022). Chronic form of venous insufficiency (disease). "In the skin of patients affected by severe chronic venous insufficiency (CVI), an elevated gene expression for MMP-1, MMP-2, MMP-9, and MMP-13 has been demonstrated." (PMID 35456498, 2022).